SLURP1 (secreted LY6/PLAUR domain containing 1)
Diseases named in the same sentence as SLURP1 in open-access papers (continued):
Sharing a sentence is not in itself a finding about the gene and the disease.
cancer (20 papers, 2011 to 2025). A tumor composed of atypical neoplastic, often pleomorphic cells that invade other tissues. "However, further investigations are required to fully understand the mechanisms underlying SLURP1’s ability to prevent cancer proliferation and its protective function in humans." (PMID 37896222, 2023). "Therefore, SLURP1 must have an underlying signaling pathway that diminishes cancer cell proliferation other than cell cycle arrest." (PMID 37896222, 2023). "Subgroup analysis revealed that Slurp1 exhibited its highest expression levels in the cancer cell subsets and its second highest in the fibroblast subsets and that its expression was minimal in the other cell types." (PMID 39840525, 2025). "Collectively, our findings provide compelling evidence that treatment with lobeline results in a significant enhancement of both the mRNA and protein levels of SLURP1 in cancer cells." (PMID 39840525, 2025). "There was no such correlation when survival was examined with respect to SLURP1 in cancer cells alone, or TβRII in monocytes alone, or TβRII in neutrophils alone (Supple fig." (PMID 40568095, 2025). "We further examined the correlation of patient survival with the dormancy regulatory mechanisms we uncovered, including increased SLURP1 in cancer cells and downregulation of TβRII in monocytes and neutrophils (left)." (PMID 40568095, 2025). "For the maximum therapeutic outcome of SLURP1, it should act upon the surface of cancer cells where the nAChRs are distributed in abundance." (PMID 37896222, 2023). "The diversity of the physiological roles of SLURP-1 found in keratinocytes and immune and cancer cells has been recently reviewed." (PMID 38069271, 2023). "As a result, using such a target-oriented delivery of anti-inflammatory peptide, SLURP1 shows promise for future cancer treatments." (PMID 37896222, 2023). "Secreted Ly6/uPAR-related protein 1 (SLURP-1) is a secreted Ly6/uPAR protein that negatively modulates the nicotinic acetylcholine receptor of α7 type (α7-nAChR), participating in control of cancer cell growth." (PMID 34595181, 2021). "Anyway, because for various Ly6 proteins such as ws-Lynx1 or SLURP-1 are carried out versatile tests against cancer and neurodegenerative diseases we believe that a set of obtained and characterized synthetic fragments can also be useful." (PMID 33374963, 2020). "The cancer cells for each patient were divided into SLURP1− or SLURP1+ subsets." (PMID 40568095, 2025). "Additionally, lobeline upregulates mRNA expression of secreted Ly‐6/UPAR‐related protein 1 (Slurp1) in cancer cells." (PMID 39840525, 2025). "Thus, snake α-cobratoxin from Naja kaouthia, human-secreted epithelial protein SLURP-1, as well as human protein Lynx1 found in the nervous system, skin, and lungs were demonstrated to be effective anti-cancer agents." (PMID 41590700, 2025). "Moreover, gene‐heatmap analysis indicated a higher expression of Slurp1 in all six cancer cell subsets in mice treated with lobeline than in those subsets in mice treated with PBS." (PMID 39840525, 2025). "SLURP1, a secreted Ly6/uPAR related protein, disrupts uPA (urokinase plasminogen activator)-mediated cell proliferation in corneal homeostasis 53, 54 and shows anti-proliferation properties in cancer." (PMID 40568095, 2025). "Furthermore, the combined treatment significantly upregulated SLURP1 expression in tumors and suppressed cancer cell proliferation." (PMID 39840525, 2025). "Thus, increased level of SLURP-1 in the blood or other tissues of the body can be considered a promising strategy for cancer therapy." (PMID 37854069, 2023). "Nicotine has been shown to promote cancer growth, whereas SLURP1 exhibits inhibitory properties." (PMID 37896222, 2023).
cancer (continued). "Consideration of SLURP1 as a protective protein has also been reported in clinical cohort studies, where it was observed that cancer patients with high levels of SLURP1 in their plasma had a greater chance of surviving than cancer patients with low levels of SLURP1." (PMID 37896222, 2023). "These supplementary partners can be either the cell membrane surrounding the nicotinic acetylcholine receptor or other receptors, for example, receptor-tyrosine kinases in the case of nicotinic acetylcholine receptors and the human SLURP-1 protein in cancer cells." (PMID 37888643, 2023). "Activation of plasminogen could promote cancer cell proliferation; thus, inhibition of this pathway by SLURP1 could have huge implications on cancer inhibition." (PMID 37896222, 2023). "Thus, SLURP-1 can be considered a prototype antitumor drug, but its effect on cancer and normal cells, its targets and active centers should be studied in details." (PMID 34595181, 2021). "In addition, Slurp1 is also expressed in fibroblasts except for cancer cells." (PMID 39840525, 2025). "In addition, it has been reported that the secreted Ly-6/uPAR-related protein-1 (SLURP-1), an endogenous peptide antagonist of α7nAChR, has an anti-proliferative effect and significantly suppresses the development and progression of cancer-related features in various cancer cell lines." (PMID 41003004, 2025). "In addition, SLURP-1 was shown to abolish STAT3 upregulation in cancer cells." (PMID 33815383, 2021). "Further, recombinant SLURP1 treatment decreased FAK phosphorylation and increased the P-p38 to P-ERK ratio, characteristic of dormant cancer cells." (PMID 40568095, 2025). "We next generated a dormancy gene signature from our findings that included the expression levels of SLURP1, INFGR2, KLF4, and CD200 in cancer cells along with CD200R1 in NK cells and tested for links to immunotherapy responses." (PMID 40568095, 2025). "Along with other cell-cycle inhibitors, such as PSCA, NDRG2 and SLURP1, they were downregulated in HNSCC, aligning with the hyper proliferative nature of cancer cells." (PMID 37686696, 2023). "Most of the genes showed an increase in gene expression during the stages of cancer, particularly in the last two stages, except for NDRG2, FAM3D, KRT78, SLURP1, MUC21, and CRCT1, which showed a significant drop in gene expression compared to normal tissue." (PMID 37917867, 2023). "Although the precise pathway leading to the induction of SLURP-1 is not fully understood, these findings suggest SLURP-1 should be considered for the development of new treatment approaches for cancer." (PMID 34202925, 2021). "Indeed, doxorubicin alone,and in combination with SLURP-1, suppresses the expression of this receptor intumors.EGFR mediates the growth, migration andsurvival of cancer cells." (PMID 40264586, 2025). "Since human SLURP1 has never been tested for its effect on cancer tumors, in the present study, SLURP1’s effect on mice CT26 colon cancer tumor model was evaluated." (PMID 37896222, 2023). "However, in tumors of the SLURP-1-treated mice, we observed a significant increase in expression of the genes coding α7-nAChR (CHRNA7), pro-oncogenic integrin α5 (ITGA5), and ceramide kinase (CERK), which are responsible for growth and migration of cancer cells." (PMID 37854069, 2023).
infection (3 papers, 2021 to 2024). The state of being infected such as from the introduction of a foreign agent such as serum, vaccine, antigenic substance or organism. "Whether the enhanced SLURP1 secretion is a universal phenomenon upon infection is very interesting and warrants further investigation." (PMID 34721415, 2021).
skin disorder (3 papers, 2015 to 2022). Any deviation from the normal structure or function of the skin or subcutaneous tissue that is manifested by a characteristic set of symptoms and signs. "Disruptions in SLURP1 were associated with skin disorders, such as Mal de Meleda disease, and neurological symptoms after IR exposures." (PMID 36005150, 2022).
neurodegenerative disease (2 papers, 2020 to 2023). A disorder of the central nervous system characterized by gradual and progressive loss of neural tissue and neurologic function. "Whatever their mode of binding, the analyzed SLURP-1 forms interact with the indicated nAChR subtypes and may find applications in developing drugs acting on these receptors involved in pain, inflammation and neurodegenerative diseases." (PMID 38069271, 2023).
head and neck tumors (1 paper, 2021). "The mechanism of SLURP1 and CLDN10 in head and neck tumors deserves further study." (PMID 34631779, 2021).
immune dysfunction (1 paper, 2014). "Genetic deficiency in SLURP-1 leads to defects in keratinocyte differentiation and immune dysfunction, resulting in Mal de Maleda, a skin disease resembling AD of the hands and feet." (PMID 25464511, 2014).
SLURP1 also shares sentences with these, for which no sentence is quoted: genetic diseases (2 papers); liver fibrosis (2); Sepsis (2); skin cancer (2); basal cell carcinoma (1); Cirrhosis (1); colon (1); dermatitis (1); diffuse palmoplantar keratoderma (1); eczema (1); esophageal cancer (1); esophageal squamous cell carcinoma (1); food allergy (1); glioblastoma (1); glioma (1); head and neck squamous cell carcinoma (1); hypertriglyceridemia (1); ichthyosis (1); Infertility (1); leukemia (1); lymphoma (1); meningitis (1); myeloma (1); Obesity (1); osteosarcoma (1); ovarian carcinoma (1); Palmoplantar hyperkeratosis (1); pancreatic ductal adenocarcinoma (1); Parkinson disease (1); periodontitis (1).
A further 6 diseases each share a sentence with SLURP1 in 1 paper.